LHCGR (luteinizing hormone/choriogonadotropin receptor)
Diseases named in the same sentence as LHCGR in open-access papers (continued):
Sharing a sentence is not in itself a finding about the gene and the disease.
Down syndrome (5 papers, 2005 to 2014). "The dramatic reduction of full-length LHCGR expression in Down’s syndrome chorionic villi points toward a physiological role for sLHCGR in hCG signalling at early pregnancy." (PMID 24906955, 2014). "This view is supported by studies showing a dramatic reduction of full-length LHCGR expression in Down’s syndrome chorionic villi compared to chromosomally normal pregnancies." (PMID 23245345, 2012). "The goal of this study was to examine the placental expression of the LHCGR mRNA and functional receptor protein expression with respect to serum hCG concentrations in Down's syndrome pregnancies." (PMID 15969756, 2005). "The present study suggests that the ratio of the serum LHCGR forms (sLHCGR:hCG-sLHCGR) could serve as a superior independent marker for Down’s syndrome and significantly increase the efficiency of the current prenatal screening program without compromising the false positive rate." (PMID 24906955, 2014). "Previous studies showed that soluble LHCGR/hCG-sLHCGR concentrations in serum or plasma combined with PAPP-A and free βhCG significantly increased the sensitivity of Down’s syndrome screen at early pregnancy without altering the false positive rate." (PMID 24906955, 2014).
endometriosis (5 papers, 2022 to 2025). The growth of functional endometrial tissue in anatomic sites outside the uterine body. "Collectively, these results indicated that the decline of LHCGR may result in LUFs, and this may be associated with endometriosis-associated infertility." (PMID 35600595, 2022). "Taken together, this study demonstrated that the LHCGR signaling was reduced in GCs of endometriosis and resulted in a decrease in gonadotropin-induced COX-2 expression." (PMID 35600595, 2022). "Taken together, it is possible that endometriosis induces attenuation of LHCGR during folliculogenesis." (PMID 35600595, 2022). "Here, we provide evidence that attenuation of LHCGR in granulosa cells is involved in the increased incidence of LUFs in surgical-induced endometriosis mice." (PMID 35600595, 2022). "The clinical observation that patients with endometriosis have dysfunctional LHCGR expression, further suggesting a failure in the mechanism associated with LH action in the ovulation process." (PMID 35600595, 2022). "The expression of LHCGR was decreased in the GCs of endometriosis mice." (PMID 35600595, 2022). "Therefore, we conjecture that the endometriosis-related abnormal actions of LHCGR modulate downregulation of COX-2 in GCs, then results in reduced ovulation with impaired follicle rupture." (PMID 35600595, 2022). "In this study, we found that LHCGR expression decreased in endometriosis granulosa cells." (PMID 35600595, 2022). "Although inactivating mutation of luteinizing hormone/choriogonadotropin receptor (LHGCR) results in LUFs, whether LHCGR contributes to promoting LUFs in endometriosis remains elusive." (PMID 35600595, 2022). "Although previous studies have claimed that inhibitors and environmental endocrine disruptors may play an important role in impaired ovulation, dysfunctional gene expression in patients with endometriosis draws focus on the expression of LHCGR." (PMID 35600595, 2022). "Nevertheless, we documented that the expression of LHCGR was decreased in EMs granulosa cells 48 h after PMSG in this study and it may be a key mediator of endometriosis-associated LUFs." (PMID 35600595, 2022).
hyperandrogenism (5 papers, 2013 to 2019). Excessive secretion of androgens from the adrenal glands or gonads. "LHCGR was identified in this pathway, which is a known susceptibility loci of PCOS discovered through GWAS, having an association with hyperandrogenism." (PMID 26308735, 2015). "Pathophysiological functions of genes are primarily responsible for the synthesis of proteins that have role in PCOS before hyperandrogenism including GnRHR, FSHβ, FSHR, LHCGR, CYP19A1, HSD17B, AR and SHBG, and their effects in PCOS of human have been confirmed." (PMID 30944702, 2019).
Obesity (5 papers, 2015 to 2026). Accumulation of substantial excess body fat. "To confirm that our finding of LHCGR overexpression is a PCOS-specific effect, we identified GEO datasets that could be analyzed with either obesity or insulin sensitivity as a dichotomous trait." (PMID 26305227, 2015). "In analysis stratified by obesity, LHCGR was overexpressed only in non-obese PCOS women." (PMID 26305227, 2015).
adenoma (4 papers, 2015 to 2023). A neoplasm arising from the epithelium. "In their study, primary zona glomerulosa-like adenoma cells transiently transfected with the CTNNB1 mutations found in the patients induced the expression of LHCGR." (PMID 36926028, 2023). "LHCGR was diffusely expressed in adrenal tissues and was prominent in adenoma harboring CTNNB1 mutations." (PMID 28102204, 2017). "More recently, overexpression of LHCGR required combined mutations of GNA11 and GNAQ in CTNNB1-mutant aldosterone-producing adenomas presenting in puberty, pregnancy or menopause." (PMID 36926028, 2023). "The transition from hyperplasia to adenoma required LH/LHCGR signaling, but thereafter tumor progression became gonadotropin independent." (PMID 30400009, 2019). "Our recent findings on inhα/Tag mice showed that, besides LHCGR, the adrenocortical tumors express Gnrhr, and SV40Tag expression alone is only able to cause adrenocortical hyperplasia but not adenomas." (PMID 30400009, 2019).
adrenal adenomas (4 papers, 2020 to 2024). "LH/HCG GPCR (LHCGR) and GnRHR can also be ectopically expressed in adrenal adenomas or adrenal hyperplasia leading to hyperaldosteronism." (PMID 36926028, 2023). "This original case was followed by the description of 3 cases with primary hyperaldosteronism during pregnancy (n=2) and menopause (n=1), showing LHCGR and GnRHR overexpression in adrenal adenomas by microarray analysis and qPCR." (PMID 36926028, 2023). "Pregnancy-induced Cushing’s syndrome (CS) with an adrenocortical adenoma overexpressing luteinizing hormone (LH)/human choriogonadotropin (hCG) receptors (LHCGR) has been rarely reported in the literatures." (PMID 32393232, 2020). "We hypothesize that, on the one hand, the physiological increase in hCG during pregnancy may activate LHCGR in adrenal adenomas, thereby accelerating tumor growth and leading to increased synthesis and secretion of cortisol." (PMID 39010034, 2024). "Pregnancy‐induced CS overexpressing LHCGR, elevated HCG levels during pregnancy stimulate aberrant LHCGR expression in adrenal adenoma tissue, leading to the activation of the cyclic adenosine monophosphate (cAMP) and protein kinase A (PKA) pathways." (PMID 38475883, 2024).
familial male-limited precocious puberty (4 papers, 2015 to 2021). Familial male limited precocious puberty (FMPP) is a gonadotropin-independent familial form of male-limited precocious puberty, generally presenting between 2-5 years of age as accelerated growth, early development of secondary sexual characteristics and reduced adult height. "Activating mutations resulting in single amino acid replacements in LHCGR were the first to be described in patients with familial male-limited precocious puberty (FMPP)." (PMID 26483755, 2015).
hypogonadism (4 papers, 2011 to 2023). A disorder characterized by decreased function of the gonads. "The importance of the amino acid sequence encoded by exon 10 is provided by the example of a LHCGR deletion involving the whole exon 10 found in a male patient affected by hypogonadism." (PMID 28452938, 2017). "The link between hypogonadism and LHCGR functions was first demonstrated by partial purification of Mr 30 K-60 K serum proteins that were found to competitively inhibit the hormone binding to the LH receptor and affect testosterone production in uremic boys." (PMID 22195987, 2011).
Type 2 Diabetes (4 papers, 2013 to 2025). "Gene association studies have so far identified 16 candidate loci involved in PCOS, including genes involved in gonadotropin action (LHCGR and FSHR), metabolism and sexual development (ESR1), insulin signaling and type 2 diabetes (INSR, THADA, HMGA2) or cell proliferation (YAP1 and SUMO1P1)." (PMID 40551954, 2025).
amenorrhea (3 papers, 2018 to 2023). The absence of menses in a woman who has achieved reproductive age. "The same inactivating LHCGR mutation was previously reported in 46,XY DSD and 46,XX primary amenorrhea." (PMID 29670578, 2018).
colon cancers (3 papers, 2017 to 2021). "Mutations in genes encoding GPCRs are observed in approximately 20% of cancers, including mutations in TSHR in thyroid cancer, luteinizing hormone receptor (LHCGR), and follicle stimulating hormone receptor (FSHR) in breast, lung, and colon cancers." (PMID 31072060, 2019). "Recent cancer genome mutation analyses have revealed that GPCRs are mutated in roughly 20% of all malignancies, including mutations in the thyroid hormone receptor (TSHR), the luteinizing hormone receptor (LHCGR), and follicle-stimulating hormone receptor (FSHR) in breast, lung, and colon cancers." (PMID 34943797, 2021).
Cushing syndrome (3 papers, 2016 to 2023). Cushing's syndrome (CS) encompasses a group of hormonal disorders caused by prolonged and high exposure levels to glucocorticoids that can be of either endogenous (adrenal cortex production) or exogenous (iatrogenic) origin. "In GIP-dependent primary bilateral macronodular adrenal hyperplasia with Cushing’s syndrome, KDMIA mutations were found to be responsible for ectopic GIPR expression but could also result in increased expression of LHCGR." (PMID 36926028, 2023). "In addition, LHCGR is discussed to be involved in the manifestation of the pregnancy induced Cushing’s Syndrome due to adrenocortical LHCGR overexpression that may lead to adrenocortical hyperfunction." (PMID 27716033, 2016).
Leydig cell hypoplasia (3 papers, 2019 to 2024). A condition in males that affects sexual development. "Inactive variants of the LHCGR gene cause Leydig cell hypoplasia (LCH), which is a rare disease and one of the causes of disorder of sexual differentiation (DSD) in males." (PMID 30444213, 2019). "Leydig cell hypoplasia (LCH) is a rare autosomal recessive disorder (OMIM# 238,320) caused by inactivating variants of the luteinizing hormone/choriogonadotropin receptor (LHCGR) gene in genetic males." (PMID 38526829, 2024).
ovarian dysfunction (3 papers, 2021 to 2023). The inability of the ovaries to function. "CLOCK, BMAL1, and E4BP4 can be entrained by hypoxic signaling, which synergistically promotes LHCGR reduction in GCs and results in ovarian dysfunction." (PMID 36620217, 2022).
seminoma (3 papers, 2020 to 2025). A radiosensitive malignant germ cell tumor found in the testis (especially undescended), and extragonadal sites (anterior mediastinum and pineal gland). "The diagnostic value of serum LHCGR for detection of relapse was investigated in 23 patients with non-seminoma and 20 patients with seminoma followed longitudinally after orchiectomy." (PMID 32466562, 2020). "In 112 patients with seminoma, serum LHCGR levels were associated with tumor size; patients with large tumors above 5 cm in diameter had higher serum concentration of LHCGR than men with small tumors <2 cm (p = 0.04)." (PMID 32466562, 2020). "In accordance, another study showed that a patient with an activating mutation in LHCGR developed a seminoma, which supports a direct link between GCNIS/seminoma risk and LHCGR." (PMID 32466562, 2020). "Direct comparison between primer sets targeting extracellular and intracellular LHCGR regions highlighted the possible presence of truncated and full-length variants, detectable in seminomas and some GCNIS specimens, while NSTs showed low or undetectable LHCGR expression." (PMID 40723290, 2025). "The proposed direct stimulatory effect is supported by GCNIS and seminoma development in two patients with activating mutations in LHCGR, the release of LHCGR from seminoma cells, and the positive link between serum LHCGR and LDH and tumor burden in seminoma patients." (PMID 32466562, 2020). "Nevertheless, elevated serum LHCGR levels in patients with larger seminomas suggest a possible prognostic marker." (PMID 40723290, 2025). "LHCGR has recently been considered as a prognostic marker for a subset of tumors, including the growth of testicular germ cell tumors (seminomas)." (PMID 39056799, 2024). "Two different antibodies targeting the extracellular region showed expression of LHCGR in seminoma cells by IHC although with different subcellular localizations." (PMID 32466562, 2020). "LHRsc revealed expression of LHCGR in the membrane of seminoma cells, whereas the LHR029 antibody presented with moderate to strong cytoplasmic staining of the seminoma cells." (PMID 32466562, 2020). "LDH is a non-specific marker for seminoma and men with elevated LDH (>205 U/L) also had higher serum LHCGR than seminoma patients with normal LDH levels (p = 0.009)." (PMID 32466562, 2020). "The link with tumor burden was corroborated by showing that serum LHCGR was higher in seminoma patients with elevated serum LDH, a marker which has previously been associated with more advanced disease and larger tumor burden." (PMID 32466562, 2020). "Instead, LHCGR levels were significantly higher in patients with elevated AFP, which indicates that LHCGR in non-seminoma either originates or is related to the yolk sac tumor component." (PMID 32466562, 2020). "Finally, the fact that LHCGR expression is higher only in seminoma patients with elevated LDH serum marker further corroborates the connection with tumor burden." (PMID 40723290, 2025). "Instead, serum LHCGR levels were significantly higher in 112 patients with a seminoma >5 cm or elevated serum lactate dehydrogenase (LDH) compared with men harboring smaller seminomas <2 cm or normal LDH levels." (PMID 32466562, 2020). "In humans, LHCGR has been found in serum and follicular fluid of women and by proteomics in serum from men and women but could it also be released from seminoma cells and be measured in serum?" (PMID 32466562, 2020). "In accordance, LHCGR was also detected in 0–40% of the D2-40 positive seminoma cells." (PMID 32466562, 2020). "Detection of LHCGR in the medium from TCam2 cells indicates that seminoma cells in patients also may release LHCGR." (PMID 32466562, 2020).
seminoma (continued). "The presence of a functional LHCGR receptor on the surface of seminoma cells opens the possibility of a direct stimulatory effect on tumor cells upon hCG stimulation, confirmed by both extensive literature data and the presence of sporadic GCNIS in patients harboring activating LHCGR mutations." (PMID 40723290, 2025). "The functional significance of all the LHCGR isoforms in seminoma remains to be established, but the presence of additional likely unspecific signals with the primer set targeting exon 2–4 highlights that caution is warranted during assessment of LHCGR expression." (PMID 32466562, 2020). "Combined, these novel findings suggest that LHCGR may be directly involved in the progression and growth of seminomas, and our retrospective pilot study suggests that serum LHCGR may have some prognostic value in men with seminoma." (PMID 32466562, 2020). "However, the higher serum LHCGR in patients with large seminomas compared with patients having small tumor volumes suggests that serum LHCGR may have some prognostic value in seminoma patients." (PMID 32466562, 2020). "Staining of the seminoma-derived TCam2 cells with LHR029 and LHRsc showed a cytoplasmic/membranous expression of LHCGR." (PMID 32466562, 2020). "Presence of exon 2–4 and exon 11 in both seminoma and some GCNIS specimens suggests that LHCGR is available either as full-length or at least possesses the ability to signal intracellularly." (PMID 32466562, 2020). "Presence of LHCGR in GCNIS and seminoma was verified by western blot using three different antibodies targeting different parts of the LHCGR." (PMID 32466562, 2020). "Here, we established that LHCGR is expressed in a fraction of seminoma cells and germ cell neoplasia in situ (GCNIS), and the seminoma-derived cell line TCam2 released LHCGR into the medium." (PMID 32466562, 2020). "A prerequisite for functional relevance is presence of the receptor, which was verified by showing expression of LHCGR at mRNA and protein level in some GCNIS and seminoma specimens from TGCT patients." (PMID 32466562, 2020). "Moreover, the presence of various LHCGR isoforms in certain GCNIS and seminomas has been recently described in the literature and confirmed to be present at both transcriptional and translational levels." (PMID 40723290, 2025). "LHCGR antibodies have a poor reputation and here we tested three different antibodies that all showed a similar band size of LHCGR around 50 kDa in normal testis, GCNIS, seminoma, and EC." (PMID 32466562, 2020). "Men with seminoma and non-seminoma tended to have higher serum LHCGR levels compared with men with GCNIS although they were not significantly different." (PMID 32466562, 2020). "LHR029 also detected LHCGR in the cytoplasm of a subset of SOX2 positive EC cells while LHRsc showed no expression in non-seminoma components." (PMID 32466562, 2020). "The risk of relapse in seminoma patients was associated with tumor size (p = 0.03), high LDH levels (p = 0.002), while serum LHCGR and hCG were not significantly different between patients with and without relapse." (PMID 32466562, 2020). "qPCR showed expression of LHCGR in NT, GCNIS, and in specimens with seminoma." (PMID 32466562, 2020). "Serum LHCGR was not significantly different between patients with and without relapse in both seminoma and non-seminoma patients." (PMID 32466562, 2020). "Presence of LHCGR in human serum was supported by conducting western blot on serum from two healthy men (with a low and high serum LHCGR level) and two patients with either seminoma or non-seminoma and high serum LHCGR levels measured by a specific ELISA platform." (PMID 32466562, 2020). "qPCR of a larger number of specimens corroborated the presence of LHCGR in seminoma and GCNIS specimens, while non-seminomas had low LHCGR or undetectable expression." (PMID 32466562, 2020).
seminoma (continued). "In contrast, there was no consistent expression of LHCGR in non-seminoma components and no growth regulatory effects of LH or hCG were found on NTera2 cells in vitro or in vivo, suggesting that seminoma and GCNIS appear to be the main targets for LHCGR agonists." (PMID 32466562, 2020).
adrenal tumors (2 papers, 2021). "Finally, displaced LHCGR without the transmembrane-domain has been shown in malignant adrenal tumors." (PMID 33809538, 2021). "Furthermore, some cases of LHCGR-positive adrenal tumors or macronodular hyperplasia did not respond to hCG or LH." (PMID 34863285, 2021).
cryptorchidism (2 papers, 2023 to 2025). The failure of one or both testes of a male fetus to descend from the abdomen into the scrotum during the late part of pregnancy. "LCH is a rare autosomal recessive DSD caused by LH/chorionic gonadotropin receptor gene (LHCGR) mutation in phenotypically female individuals with 46, XY karyotype and cryptorchidism." (PMID 41163677, 2025).
cyst (2 papers, 2023). A sac-like closed membranous structure that may be empty or contain fluid or amorphous material. "Whereas LHCGR mRNA abundance was very low in both types of cysts, the protein levels in IPC was higher than SOC cyst (p < 0.05)." (PMID 37173342, 2023). "Abundance of mRNA encoding PGRb, AR and STAR was significantly increased in GCs from cysts compared to control GCs, and mRNA levels for both LHCGR and FSHR were significantly lower in cyst CGs in comparison to controls (p < 0.05)." (PMID 37760251, 2023). "Indeed, mRNA levels for both LHCGR and FSHR were significantly lower in our cyst group samples in comparison to controls." (PMID 37760251, 2023).